CD4 (CD4 molecule)
Diseases named in the same sentence as CD4 in open-access papers (continued):
Sharing a sentence is not in itself a finding about the gene and the disease.
tumor (continued). "In their studies, tumor cells transduced with costimulatory molecules in the presence or absence of additional HLA class II molecules and the invariant chain (Ii), were capable of producing novel tumor-derived Ags and subsequent stimulation of CD4+ T cells." (PMID 26807308, 2015). "Our goal is to improve immune responses and anti-tumor effects against a synthetic, multi-epitope, long peptide from rat Her2/neu (rHer2/neu) using the help of CD4+ T cells and appropriate adjuvant in a mouse tumor model." (PMID 26556756, 2015). "Tumor antigen-specific CD4+ T cells generally orchestrate and regulate immune cells to provide immune surveillance against malignancy." (PMID 26447332, 2015). "A Xenopus VEGF DNA vaccine that was protective and therapeutic in several tumor models in mice, an effect that was mediated by anti-tumor activity of CD4+ lymphocytes." (PMID 26510973, 2015). "Although the HER-3 protein is expressed on tumor cells, presentation of the HER-3872−886 peptide on tumor cells through the endogenous antigen-processing machinery is required for CD4 T cell recognition." (PMID 26538233, 2015). "This subset of tumor-specific CD4+ T cells has the ability to promote OC activation and induce osteolytic bone disease even before seeding of tumor cells in the bone microenvironment." (PMID 26000310, 2015). "The tumor microenvironment alters the effector phenotype of CD4 T cells and the balance with regulatory T cells." (PMID 26146642, 2015). "No significant suppression on the Ag-dependent proliferation of ENO1- or OVA-specific CD4+ T cells was observed using Treg cells isolated from the spleens of tumor-free mice." (PMID 26551021, 2015). "In some experimental models, transfer of either CD4 or CD8 cells activated TDLN cells induced in vivo tumor regression, while in other models CD4 alone or CD8 alone was therapeutically ineffective." (PMID 26090481, 2015). "The number of CD4+ cells was significantly increased in tumor tissue compared with healthy donor tissue [62 (52...72) vs. 12 (4...32)]." (PMID 26413839, 2015). "The levels of TGF-β appear to be higher in the culture containing tumor-associated Treg cells and ENO1-specific CD4+ T cells as compared to that containing OVA-specific CD4+ T cells." (PMID 26551021, 2015). "In the present study, we show that TLR7 activation by Loxoribin induces tumor regression in vivo, and these anti-tumor effects are mediated by promoting CD4+T cell proliferation and reversing Treg-mediated suppression." (PMID 25593198, 2015). "It is possible that activation of the OX40 receptor increases the function of tumor-specific CD4-positive T cell and allows more efficient effector function as well as the generation of CD8-positive T-cell memory." (PMID 26579494, 2015). "Similar findings were found in glioblastoma tumours, where all tTregs (CD4+FoxP3+Helios+) were GITR+." (PMID 25961057, 2015). "The presence of CD4 + CD25- T cells in the peripheral blood as well as in the tumor site leads to a significant increase in the number of regulatory T cells (Treg cells, CD4 + CD25+)." (PMID 25975566, 2015). "In our study, we found higher numbers of CD4+ T cells in HPV-positive tumor samples, with slightly higher proportions of Th1 cells and a significantly higher number and frequency of naïve T cells." (PMID 25949860, 2015). "γδ-T cells show positive correlations with CD4+ FOXP3+ T cells, and are associated with poor outcomes and advanced tumor stage, as well as low disease-free and overall survival in patients with breast cancer." (PMID 26300242, 2015). "The synergistic effects of Treg depletion plus TIM-3 blockade resulted in significant and sustained tumor regression with concomitant emergence of CD4+ and CD8+ effector T cells that played a major role in mediating tumor regression." (PMID 26492563, 2015).
tumor (continued). "Whereas PD-1 was frequently expressed on CD8+ and CD4+ T cells in all of the tissues analyzed, particularly in the peripheral blood, control lymph nodes, metastatic lymph nodes and tumor tissue, Tim-3 was mainly expressed on tumor-infiltrating T-lymphocytes." (PMID 25949860, 2015). "On the other hand, CD4+ T lymphocytes form a large fraction of tumor-infiltrating lymphocytes and play an important role in the immune surveillance of the tumor." (PMID 25801067, 2015). "Here, the authors demonstrate that this phenomenon is at least partially due to an overproduction of IL-6 caused by ageing and its inhibitory effect on Th1 differentiation of tumour-specific CD4 T cells." (PMID 25850032, 2015). "T cells were gated for memory markers (CD62L and CD44) and CD4/CD8 ratio by gating on live singlet CD3+ T cells.The CD4/CD8 T cell ratio was compared between tumor bearing NCF1*/* and NCF1*/+ mice." (PMID 26076008, 2015). "Previous studies in mice have demonstrated that tumor-specific CD4+ T cells can be rendered anergic by exposure to established tumors in vivo." (PMID 25875653, 2015). "Transcriptional signatures of tumour-infiltrating T cells were indicative of reduced proliferation, and this corresponded to decreased frequencies of tumour-infiltrating CD4 helper T cells and CD8 memory cytotoxic T cells." (PMID 26146524, 2015). "therapy with adenovirus expressing GM-CSF (ONCOS-102), there was increased infiltration of CD4+/CD8+ cells into the tumour microenvironment." (PMID 26633468, 2015). "In patients, reports indicated that BRAF-inhibitors induced tumor Ag expression and the infiltration of CD8+ and CD4+ T cells in metastases shortly after the initiation of treatment, which was followed by a reduction in tumor size." (PMID 25709607, 2015). "There were significantly increased cumulative hazard ratios with the increasing follow-up years for mortality and relapse in the cancer patients containing high levels of tumor-infiltrating CD4+ T cells (CD4+ T cells > 16)." (PMID 25968569, 2015). "It is established that an effective anti-tumor immune response requires the involvement of both CD4+ and CD8+ T cells." (PMID 25968569, 2015). "Cx43 channels have also been involved in the regulation of T cell maturation and proliferation, in particular of CD4/Foxp3 double positive regulatory T cells and in the cross-presentation of tumor or viral peptides between cells." (PMID 25815348, 2015). "The expression of chemokine receptors binding the tumour signature chemokines defined above was compared on Foxp3+ and Foxp3− CD4+ T cells." (PMID 25495686, 2015). "Expression of the inflammatory chemokine receptors, CCR1, CCR2, CCR3, CCR5 and CX3CR1, was significantly enriched on both Foxp3+ and Foxp3− CD4+ T cells within the tumours when compared with spleens and lymph nodes." (PMID 25495686, 2015). "The results showed that HER-3-reactive CD4 T cells directly reacted with tumor cells in an HLA-DR-restricted manner." (PMID 26538233, 2015). "CD4+ Th2 lymphocytes elicit anti-tumor activity by releasing IL-5 and activation of eosinophils with tumoricidal properties." (PMID 25801067, 2015). "The expression of CD3+CD4+ T cells were significantly increased in advanced tumor stage, large tumor size and positive lymph nodes metastasis, compared to that in early groups." (PMID 26587366, 2015). "MCSCs can be identified and eliminated by CD8+ and CD4+ T lymphocytes, and the immunosuppressive effects of MCSCs can be overcome in mice tumor models." (PMID 26566931, 2015). "CD4+ T cells carry complex roles within tumor microenvironments, with context-dependent immune responses influenced by oncogenic drivers and the presence of inflammation." (PMID 26583116, 2015). "MDSCs engage several diverse strategies to suppress tumor growth by inhibiting tumor cell cytotoxicity mediated by NK cells and by blocking the activation of tumor-reactive CD4+ and CD8+ T cells." (PMID 26284197, 2015).
tumor (continued). "We examined the effect of CD4+ T-cell-mediated antitumour vaccination using MCA205 tumour cells expressing ovalbumin (OVA) as a surrogate antigen (hereafter referred to as MCA-OVA)." (PMID 25850032, 2015). "In young mice, tumour outgrowth was prevented by vaccination with OVA peptide recognized by major histocompatibility complex (MHC) class-II-restricted CD4+ T cells (referred to as OVA-IIp)." (PMID 25850032, 2015). "Most of the studies examining tumor-infiltrating CD4+ T cells as possible prognostic markers focused on regulatory T cells." (PMID 25949860, 2015). "In mice vaccinated with ENO1 or OVA, the percentage of FoxP3+ Treg cells in total CD4+CD25+ cells of spleens from tumor-bearing mice was significantly increased compared to those from tumor-free mice." (PMID 26551021, 2015). "In early tumor stages, Th1 cells are the dominant population of CD4+ T cells, perhaps important for immunosurveillance; while in the advanced tumor stages, FoxP3+ Treg and Th17 cells become the dominant populations." (PMID 25968569, 2015). "In conclusion, our results suggest that HER-3 can induce effective helper CD4 T-cell responses that lead to direct recognition and killing of tumor cells." (PMID 26538233, 2015). "Improved understanding of the role of CD4+ T cells in anti-tumor immunity is challenging in tumor immunology research and the results have been controversial." (PMID 25968569, 2015). "CD8+ T cells recognize and destroy cancer cells while CD4+ cells aid CD8+ T cells in tumor rejection." (PMID 26413839, 2015). "It has been demonstrated that the antitumor effects of IL-12 within the tumor depend on CD4+ and CD8+ T cells, NK cells and/or NKT cells." (PMID 25682197, 2015). "Tumor antigen-specific CD4+ T cells are activated at the local tumor site when tumor-infiltrating APCs capture and cross-present tumor antigens." (PMID 26447332, 2015). "Although the majority of solid cancers do not constitutively express MHC II at significant levels and cannot be directly recognized or killed in vitro by CD4+ lymphocytes, many tumour cells can upregulate the MHC II upon stimulation with IFNγ." (PMID 26081906, 2015). "We observed a trend to an increase in the numbers of total CD4+ T cells as well as IFNγ-producing CD4+ cells (Th1 cells) in the HPV-positive tumor samples (p < 0.1)." (PMID 25949860, 2015). "CD11b+/Gr-1+ cells can facilitate tumor growth by virtue of their ability to downregulate the immune responses in subtypes of T-cells such as CD4+ and CD8+ cells; hence, the denomination of MDSCs for at least a subset of CD11b+/Gr1+ cells." (PMID 25749075, 2015). "CD4+ T cells can also mediate tumor regression in the absence of CD8+ T cells, as shown by the adoptive transfer of tumor-specific CD4+ T cells." (PMID 25993655, 2015). "The dynamic distributions of CD4+ T cell subsets in peripheral blood, spleen and draining lymph nodes were analyzed in both normal and tumor-bearing mice." (PMID 25968569, 2015). "Tumor protective immune responses developed by another short oncolytic peptide involved both CD4+ and CD8+ T cells." (PMID 26472184, 2015). "Accumulating evidence suggest that CD4+ T cells play a critical role for tumor immunity and each subset has a unique role in adaptive immune during the tumor development." (PMID 25968569, 2015). "Tumor infiltration status of CD4+CD25+ regulatory T cell was prognostic indicator of disease-free and overall survival." (PMID 26462021, 2015). "Taken together, not only complementation with tumour-specific young CD4+ T cells, but IL-6 blockade that augmented IFN-γ production was also necessary for improvement of antitumour responses in aged mice." (PMID 25850032, 2015). "The surface expression of these molecules confers to non-hematopoietic tumour cells the role of non-professional antigen presenting cells and the ability to potentially stimulate tumour-specific CD4+ T cell response." (PMID 26081906, 2015).
tumor (continued). "CD4+ T cells are critical for priming of tumor-specific CD8+ T cells and for the secondary expansion and memory of CD8+ T cells as well." (PMID 26587366, 2015). "The staining was performed using an antibody directed against a marker of endothelial cells, CD31, as well as for cytofluorimetric assessment of the level of tumor-infiltrating Treg lymphocytes (CD4+CD25high+Foxp3+)." (PMID 25801067, 2015). "Control plasmids also had an effect on Tregs, with the pEEV also having an effect on the CD4+CD25−FoxP3+ compared with the untreated tumour (P<0.05)." (PMID 25373914, 2015). "The immune cell depletion study proves that cytotoxic CD8+ T-cells (CTL) are indispensable for tumor rejection, but also demonstrates the requirement for CD4+ T cell help for effective induction of the CD8+ CTL response." (PMID 26079374, 2015). "Pretreatment of the tumor cells with dacomitinib augmented the reactivity of HER-3-reactive CD4 T cells." (PMID 26538233, 2015). "CD4+ T-cells can be functionally polarized by the cytokine milieu present in the tumor microenvironment as well." (PMID 26690220, 2015). "PD-1 promoter methylation was examined in both CD8+ T cells and CD4+ T cells because of their cooperative function in tumor surveillance." (PMID 25823822, 2015). "The results demonstrated that the percentage of CD8+ cells increased and the CD4/CD8 ratio decreased with tumor grade." (PMID 26587366, 2015). "Recently, Loxoribin, a TLR7 agonist, has been shown to be able to shrink the tumor through augmenting the proliferation of CD4+ T cells and lowering the frequency of Tregs, which is mediated by elevated IL-6 level secreted by DCs." (PMID 26683520, 2015). "To verify our observation in animal tumor models, we further analyzed the numbers of CD4+CD25HighFoxp3+ Treg cells from another group of NSCLC patients." (PMID 26551021, 2015). "Predominant infiltration of CD4+ T cells as well as CD8+ T cells was observed in tumor stroma compared to tumor islets (P < 0.001)." (PMID 26604855, 2015). "The proportion of CD4+CD25+FoxP3+ Tregs in the periphery seems to increase with tumor burden, and depletion of this population prior to challenge in the A20 lymphoma mouse model resulted in 70% tumor-free survival." (PMID 25941795, 2015). "The promotion of tumour growth by CD4+ helper T cells and CD8+ T cells is subdued with the intervention of CD40-mediated inflammatory E-cadherin + DCs." (PMID 25651850, 2015). "One such study specifically examined the role of CD4+ T cells in regulating tumor growth by implanting cells from a human lung cancer (i.e., the 201T human lung adenocarcinoma cell line) into the lungs of a strain of mice called BALB/c." (PMID 26695753, 2015). "The CD4+ T cells are of particular interest, as coadministration of CD4+ T cells to TCR-engineered adoptively administered T cells has been shown to enhance tumor infiltration of CD8+ T cells and to prevent their exhaustion." (PMID 26140230, 2015). "We first evaluated the CD4+ T cell population within the TME of metastatic Panc02 tumor bearing mice." (PMID 26515728, 2015). "Although not globally improved in all patients treated with T + C, anti-HER2 CD4+ T-cell immunity is more robust in patients achieving pCR compared with their non-pCR counterparts despite controlling for relevant demographic and tumor-related confounders." (PMID 25997452, 2015). "Next, to explore the regulatory functions of DCs in the LM-immunized tumor microenvironment, CD4+ T cell differentiation was investigated." (PMID 25826093, 2015). "We observed a correlation between high CD4+ TIL density with high tumor PD-L1 expression in metastatic lesions (p = 0.038)." (PMID 26317902, 2015). "Little is known about important CD4+ helper T cell responses against survivin, which are essential for an optimal anti-tumor immune response." (PMID 25992291, 2015).
tumor (continued). "The role of CD4+ T cells in anti-tumor immunity has recently been extensively studied in both pre-clinical animal models and clinical cancer patients." (PMID 26587366, 2015). "The aim of this study was thus to firstly evaluate the frequencies of CD4+CD25+Foxp3+ Treg cells in tumor tissue as well as in peripheral blood in patients with NIP and SSCC." (PMID 26020249, 2015). "We see a significant increase in intraepithelial FOXP3 staining for the ID8 tumor compared to the stromal compartment, despite a decrease in CD4 staining suggesting enrichment of the regulatory T cells in the intraepithelial compartment." (PMID 25992288, 2015). "Another reason of the requirement of adjuvants in vivo is that IFN-γ is indispensable to induce MHC class II molecules on tumor cells for CD4 T cell recognition." (PMID 26538233, 2015). "From immunohistochemical analysis, tumor-infiltrating CD4+FoxP3+ Tregs were decreased while tumor-infiltrating CTLs were increased in all experimental groups especially in combination groups compared with those of the control group." (PMID 26683520, 2015). "In comparison to cytotoxic CD8+ T cells that directly kill tumor cells, CD4+ T cells have a “catalytic” function within the immune system." (PMID 26844233, 2015). "Surprisingly, some CD4+ T-cell clones promoted tumor development, suggesting that besides antigen recognition, still elusive functional differences exist among virus-specific T cells." (PMID 24853673, 2014). "Anti-CD3 preactivated naïve CD4+ T cells were adoptively transferred into control or 586mel tumor-bearing Rag1−/− mice through intravenous injection." (PMID 25231413, 2014). "γδ T cells have a unique capacity to present antigens to both CD8 and CD4 T cells and potentially elicit strong adaptive anti-tumor response." (PMID 25426120, 2014). "After ex vivo restimulation, we observed a strong CD8 T cell response in tumor-free mice whereas the CD4 T cell response was low." (PMID 25101081, 2014). "CD4+ Th17 cells were long thought to be the sole cellular source of IL-17 in the human tumor microenvironment." (PMID 25197971, 2014). "For example, MHC class II-containing RAFTsomes, which are flexible nanoparticles, were able to induce CD4+ T cell responses that prevented EG.7 tumor inoculation and reduced tumor sizes in mice." (PMID 24998519, 2014). "Surprisingly, the proportion of Tregs present in tumor infiltrating CD4 cells in 1D11-treated mice was markedly increased, as compared with mice treated with control IgG1 (p = 0.01)." (PMID 24416401, 2014). "The proportion of CD4+ cells in the tumor infiltrating CD45+ leukocytes was 28.7% in 1D11-treated mice, markedly higher than that in control IgG1- treated mice (22.6%, P<0.05)." (PMID 24416401, 2014). "IFN-α treatment resulted in moderate to high numbers of CD4+ cells infiltrating close to tumor cells in 12 out of 26 metastases compared to 1 out of 10 metastases from untreated patients." (PMID 24516470, 2014). "Recently, CD4+Foxp3+ Tregs in tumor tissue were reported to have significantly increased compared with normal lung tissue." (PMID 24868562, 2014). "Collectively, these results indicate that CD4+ T cells must eliminate tumor antigen-secreting tumor cells efficiently within a short timeframe." (PMID 24782871, 2014). "The markedly anti-tumor activity of administration of IL-7/HGFb in vivo correlated with a significant increase in the number of tumor-infiltrating CD4+ and CD8+T cells." (PMID 24465710, 2014). "It is known that CTLA-4 blockade removes suppressive signals and allows expansion of tumor-specific T cells, in particular of CD4+ effectors." (PMID 25013914, 2014). "In contrast, significantly increased SA-β-Gal-positive T-cell populations were induced in preactivated naïve CD4+ T cells after co-culture with different types of tumor cell lines, indicating that tumor cells can directly induce CD4+ T-cell senescence." (PMID 25231413, 2014).